KLHL7 (kelch like family member 7)
Description:
Substrate-specific adapter of a BCR (BTB-CUL3-RBX1) E3 ubiquitin ligase complex. The BCR(KLHL7) complex acts by mediating ubiquitination and subsequent degradation of substrate proteins. Probably mediates 'Lys-48'-linked ubiquitination.
Synonyms: KLHL6; SBBI26; RP42; CISS3; PERCHING
Tractability: Small molecule: it has a high-quality binding pocket; it belongs to a druggable protein family. Antibody: its Gene Ontology location is reachable by antibodies, with high confidence. PROTAC: ubiquitination databases record sites on it.
Gene: Protein-coding gene on chromosome 7 (23,105,757 to 23,177,914, forward strand). Ensembl gene ENSG00000122550.
Subcellular location: Nucleus; Cytoplasm
Subcellular location (Human Protein Atlas): Cytosol; Nucleoplasm; Plasma membrane
Gene Ontology:
Molecular function: identical protein binding; protein binding; protein homodimerization activity; ubiquitin-like ligase-substrate adaptor activity
Biological process: protein ubiquitination; proteasome-mediated ubiquitin-dependent protein catabolic process
Cellular component: Cul3-RING ubiquitin ligase complex; cytoplasm; cytosol; nucleolus; nucleoplasm; perinuclear region of cytoplasm; nucleus
Genetic constraint (gnomAD): Loss-of-function variants: 34 observed, 57.34 expected, observed/expected ratio (o/e) 0.59, 90% interval 0.45 to 0.79. The upper end of that interval is the gene's LOEUF score, 0.79, which puts it in group 3 of 6, group 1 being the genes least tolerant of losing a copy. Missense variants: 324 observed, 685.13 expected, observed/expected ratio (o/e) 0.47, 90% interval 0.43 to 0.52. Synonymous variants: 231 observed, 231.31 expected, observed/expected ratio (o/e) 1, 90% interval 0.9 to 1.11.
Homologues: Orthologues: chimpanzee KLHL7 (100% identical), macaque KLHL7 (99% identical), guinea pig KLHL7 (99% identical), rat Klhl7 (98% identical), mouse Klhl7 (98% identical), tropical clawed frog klhl7 (96% identical), dog KLHL7 (95% identical), rabbit KLHL7 (94% identical), pig KLHL7 (93% identical), zebrafish klhl7 (75% identical). Paralogues in human: KLHL17 (29% identical), KLHL3 (28% identical), KLHL18 (27% identical), KLHL20 (27% identical), KLHL12 (27% identical), KLHL1 (27% identical), KEAP1 (26% identical), KLHL2 (26% identical), KLHL24 (26% identical), KLHL4 (26% identical), KLHL8 (26% identical), KLHL29 (26% identical), and 42 more.
Diseases named in the same sentence as KLHL7 in open-access papers:
KLHL7 is named in the same sentence as 22 diseases in open-access papers, as found by Europe PMC text mining. Sharing a sentence is not in itself a finding about the gene and the disease. The quoted sentences say what the papers report.
autosomal dominant retinitis pigmentosa (2 papers, 2013 to 2019). Autosomal dominant retinitis pigmentosa (RP) is an autosomally dominant inherited retinal dystrophy leading to progressive loss of the photoreceptors and retinal pigment epithelium and resulting in blindness usually after several decades. "Interestingly, mutationswithin the BACK domain of another Kelch-like adaptor protein, KLHL7 (Kelch-like family member 7),cause autosomal-dominant retinitis pigmentosa." (PMID 23387299, 2013).
Anxiety (1 paper, 2026). Intense feelings of nervousness, tension, or panic often arise in response to interpersonal stresses. "Multi-omic integration identified RAB27B as a driver of the anxiety-related pathway, implicating synaptic vesicle trafficking and neuroimmune regulation, while GPNMB and KLHL7 supported anxiety-independent pathways involving musculoskeletal remodeling and peripheral inflammation." (PMID 41796324, 2026).
asthenozoospermia (1 paper, 2022). "The intersection among two groups of hub genes included COPS7A, CUL3, KLHL7, and NEDD4, which can be considered the main key genes in asthenozoospermia." (PMID 36471356, 2022). "The mRNA expression of COPS7A was upregulated in patients with asthenozoospermia, but the expression of CUL3, KLHL7, and NEDD4 was downregulated in these patients." (PMID 36471356, 2022). "A Venn analysis was used to identify four key genes based on two methods, including COPS7A, CUL3, KLHL7, NEDD4, which may be potentially important genes in asthenozoospermia." (PMID 36471356, 2022). "A western blotting assay using 16 semen samples (including 8 asthenospermia and 8 normal samples) revealed similar results, indicating COPS7A was significantly upregulated in patients with asthenozoospermia, but CUL3, KLHL7 and NEDD4 were significantly downregulated compared with normal samples." (PMID 36471356, 2022). "Finally, we found that the COPS7A was significantly upregulated in patients with asthenozoospermia, but CUL3, KLHL7 and NEDD4 were significantly downregulated compared with normal samples." (PMID 36471356, 2022).
autosomal recessive congenital stationary night blindness (1 paper, 2011). "Mutations in at least one gene from each family have previously been associated with retinal disease: Klhl7 with autosomal dominant RP, Slc24A1 with autosomal-recessive congenital stationary night blindness, and Znf513 with autosomal-recessive retinitis pigmentosa (RP)." (PMID 22162623, 2011).
breast carcinoma (1 paper, 2019). "In contrast, high expression of the Kelch-like family member 7 (KLHL7) gene, which encodes for a mediator of ubiquitination, is associated with aggressive breast cancer progression." (PMID 31892232, 2019).
esophageal cancer (1 paper, 2025). A primary or metastatic malignant neoplasm involving the esophagus. "In esophageal cancer, four genes were positively correlated with IGF2BP3: KLHL7, C7orf30, NUPL2, and RAD51L3." (PMID 40765570, 2025).
glioblastoma (1 paper, 2020). The most malignant astrocytic tumor (WHO grade IV). "Re-analysis of TCGA glioblastoma RNA-seq unveils previously unreported kinase fusions (KLHL7-BRAF) and a 13% prevalence of EGFR C-terminal truncation." (PMID 32466770, 2020).
lung adenocarcinoma (1 paper, 2021). A carcinoma that arises from the lung and is characterized by the presence of malignant glandular epithelial cells. "A previously unidentified function of KLHL7 (Kelch Like Family Member 7) and KLHL11, components of the BCR (BTB-CUL3-RBX1) E3 ubiquitin ligase complex, in lung adenocarcinoma genomic instability was also suggested (q = 0.0003, 0.04, respectively)." (PMID 34070461, 2021).
pancreatic cancer (1 paper, 2024). "KLHL7-based biodegraders only degraded the anchored POI in Jurkat cells, a T cell line, while VHL depleted less efficiently the same anchored POI in pancreatic cancer cells." (PMID 38746666, 2024).
prostate carcinoma (1 paper, 2016). A carcinoma that arises from epithelial cells of the prostate gland. "KLHL7 antibodies are associated with various types of cancer, such as ovary, rectum, colon, lung and prostate cancer." (PMID 27437769, 2016).
retinal degeneration (1 paper, 2019). Degeneration of the retina. "Prior studies of KLHL7-mediated RP suggest differing onset of retinal degeneration in autosomal dominant and recessive disease." (PMID 31856884, 2019).
Retinal dystrophy (1 paper, 2019). Retinal dystrophy is an abnormality of the retina associated with a hereditary process. "Mutations in the Kelch-like protein 7 (KLHL7) represent a recently described and, to date, poorly characterized etiology of inherited retinal dystrophy." (PMID 31856884, 2019).
retinitis pigmentosa (1 paper, 2022). Retinitis pigmentosa (RP) is an inherited retinal dystrophy leading to progressive loss of the photoreceptors and retinal pigment epithelium and resulting in blindness usually after several decades. "This study was extended to two other BTB-domain proteins, i.e., KLHL21, which regulates cell cycle and cell motility, and KLHL7, the mutations of which are involved in retinitis pigmentosa." (PMID 35563538, 2022).
thyroid papillary carcinoma (1 paper, 2020). "While KLHL7-BRAF has not been reported in GBM previously, it was detected in thyroid papillary carcinoma." (PMID 32466770, 2020).
KLHL7 also shares sentences with these, for which no sentence is quoted: autosomal recessive retinitis pigmentosa (1 paper); Bardet-Biedl syndrome (1); cancer (1); glaucoma (1); glioma (1); lung carcinoma (1); retinal disease (1); sarcoma (1).